SLC7A9 (solute carrier family 7 member 9)
Description:
Associates with SLC3A1 to form a functional transporter complex that mediates the electrogenic exchange between cationic amino acids and neutral amino acids, with a stoichiometry of 1:1. Has system b(0,+)-like activity with high affinity for extracellular cationic amino acids and L-cystine and lower affinity for intracellular neutral amino acids. Substrate exchange is driven by high concentration of intracellular neutral amino acids and the intracellular reduction of L-cystine to L-cysteine. Required for reabsorption of L-cystine and dibasic amino acids across the brush border membrane in renal proximal tubules.
Synonyms: BAT1; CSNU3
Tractability: Small molecule: a structure with a bound ligand is known. Antibody: UniProt places it where antibodies can reach, with high confidence; its Gene Ontology location is reachable by antibodies, with high confidence; UniProt predicts a signal peptide or a membrane-spanning region. PROTAC: ubiquitination databases record sites on it.
Gene: Protein-coding gene on chromosome 19 (32,830,508 to 32,869,805, reverse strand). Ensembl gene ENSG00000021488.
Subcellular location: Apical cell membrane; Cell membrane
Pathways (Reactome):
Disease: Defective SLC3A1 causes cystinuria (CSNU); Defective amino acid transport by SLC7A9 causes cystinuria (CSNU)
Hemostasis: Basigin interactions
Transport of small molecules: Amino acid transport across the plasma membrane
Gene Ontology:
Molecular function: antiporter activity; broad specificity neutral L-amino acid:basic L-amino acid antiporter activity; L-cystine transmembrane transporter activity; L-lysine:L-arginine antiporter activity; neutral L-amino acid transmembrane transporter activity; protein binding; protein heterodimerization activity; peptide antigen binding; amino acid transmembrane transporter activity; transmembrane transporter activity
Biological process: L-cystine transport; neutral amino acid transport; amino acid transmembrane transport; protein-containing complex assembly; amino acid transport; basic amino acid transmembrane transport; L-alpha-amino acid transmembrane transport; L-arginine transmembrane transport; L-lysine transmembrane transport; transmembrane transport
Cellular component: apical plasma membrane; brush border membrane; plasma membrane; transmembrane transporter complex; membrane
Genetic constraint (gnomAD): Loss-of-function variants: 37 observed, 53.66 expected, observed/expected ratio (o/e) 0.69, 90% interval 0.53 to 0.91. The upper end of that interval is the gene's LOEUF score, 0.91, which puts it in group 3 of 6, group 1 being the genes least tolerant of losing a copy. Missense variants: 531 observed, 659.65 expected, observed/expected ratio (o/e) 0.8, 90% interval 0.75 to 0.87. Synonymous variants: 262 observed, 270.06 expected, observed/expected ratio (o/e) 0.97, 90% interval 0.88 to 1.08.
Gene-disease validity (ClinGen):
ClinGen rates the evidence that SLC7A9 causes each of these diseases.
cystinuria (autosomal recessive): Definitive. Cystinuria is a renal tubular amino acid transport disorder characterized by recurrent formation of kidneys cystine stones.
Homologues: Orthologues: chimpanzee SLC7A9 (99% identical), macaque SLC7A9 (92% identical), rat Slc7a9 (87% identical), mouse Slc7a9 (87% identical), rabbit SLC7A9 (86% identical), pig SLC7A9 (86% identical), dog SLC7A9 (86% identical), tropical clawed frog slc7a9 (79% identical), zebrafish slc7a9 (68% identical), Caenorhabditis elegans aat-1 (41% identical), Drosophila melanogaster mnd (41% identical), Drosophila melanogaster CG1607 (40% identical), and 8 more. Paralogues in human: SLC7A5 (44% identical), SLC7A8 (43% identical), SLC7A11 (43% identical), SLC7A6 (42% identical), SLC7A10 (41% identical), SLC7A7 (41% identical), SLC7A13 (30% identical), SLC7A4 (24% identical), SLC7A2 (23% identical), SLC7A3 (23% identical), SLC7A1 (23% identical), SLC7A14 (20% identical).
Diseases named in the same sentence as SLC7A9 in open-access papers:
SLC7A9 is named in the same sentence as 62 diseases in open-access papers, as found by Europe PMC text mining. Sharing a sentence is not in itself a finding about the gene and the disease. The quoted sentences say what the papers report.
cystinuria (54 papers, 2012 to 2026). "In cystinuria, monoallelic SLC7A9 variants represented intermediate risk factors, since they caused biochemical alterations but required additional factors for KSD occurrence, based on frequent LP/P variants in NKSFs." (PMID 41766659, 2026). "We present two pediatric cases of cystinuria caused by SLC7A9 mutations, each treated with a different cystine-binding thiol: tiopronin and D-penicillamine." (PMID 40981121, 2025). "Both type A (SLC3A1 mutations) and type B (SLC7A9 mutations) cystinuria share similar clinical courses, though males tend to experience more severe disease." (PMID 41142409, 2025). "Four cystinuria patients had a monoallelic P/LP pathogenic mutation, two in the SLC3A1 and two in the SLC7A9 genes, all of them presenting manifestations of cystinuria." (PMID 40428323, 2025). "Both patients in our report carried SLC7A9 mutations, leading to defective cystine transport and clinical manifestations of cystinuria." (PMID 40981121, 2025). "These two pediatric cases of cystinuria illustrate the phenotypic variability and management challenges associated with SLC7A9 mutations." (PMID 40981121, 2025). "Results indicated that 8% of patients exhibited positive genetic tests, notably featuring a single patient with a pathogenic mutation of SLC7A9 associated with cystinuria." (PMID 40126616, 2025). "Due to recurrent nephrolithiasis while on conservative treatment, genetic testing was pursued and revealed a homozygous pathogenic variant in the SLC7A9 gene, confirming a diagnosis of cystinuria." (PMID 40981121, 2025). "We detected biallelic pathogenic variants in SLC3A1 for two patients (type A cystinuria) and biallelic pathogenic and likely pathogenic variants in SLC7A9 for another two patients (type B cystinuria)." (PMID 40428323, 2025). "Only 1 had a KSD-associated autosomal dominant pathogenic mutation, which was for cystinuria (SLC7A9)." (PMID 40126616, 2025). "Case Presentation: Here, we report two cases of female patients diagnosed with cystinuria caused by SLC7A9 mutations." (PMID 40981121, 2025). "Eight (8%) had positive tests with only one patient found to have a pathogenic mutation associated with KSD (SLC7A9, cystinuria)." (PMID 40126616, 2025). "Mutations in the SLC7A9 (also SLC3A1) gene are a common cause of cystinuria and lead to the formation of cystine stones." (PMID 40924792, 2025). "Cystinuria occurs due to mutations in the solute carrier family 3 member 1 (SLC3A1) or the solute carrier family 7 member 9 (SLC7A9) gene that encodes the components of the cystine transporter." (PMID 37957454, 2024). "Nonetheless, the most frequent KSD-causing gene was determined to be SLC7A9, associated with cystinuria, whose diagnosis is typically achieved through a detailed urinary metabolic study and thorough stone analysis." (PMID 39596670, 2024). "First, the SLC3A1 and SLC7A9 genes were screened for cystinuria-causing mutations in the 34 patients recruited for this study." (PMID 38138969, 2023). "To date, studies on canine cystinuria have implicated variants in the functional candidate genes SLC3A1 and SLC7A9, encoding amino acid transporters involved in the excretion of cystine and known to explain approximately 70% of human cystinuria cases." (PMID 36848397, 2023). "Cystinuria caused by mutations in SLC3A1 is classified as type A cystinuria, while mutations in SLC7A9 cause type B. Most patients with cystinuria carry two mutations (AA, BB, or AB)." (PMID 38114997, 2023). "More than 20 years have passed since the identification of SLC3A1 and SLC7A9 as causative genes for cystinuria." (PMID 38138969, 2023). "Genetic variants in the SLC3A1 and SLC7A9 genes underlie cystinuria, as they encode the heavy (rBAT) and the light (b0,+AT) subunits of the cystine and dibasic amino acid transport system b0,+." (PMID 38138969, 2023).
cystinuria (continued). "Although Slc7a9 mutations have been reported to cause cystinuria, their functions in protecting proximal tubular cells against iron-induced oxidative damage and ferroptosis are unclear." (PMID 37293506, 2023). "The phenotype of Slc7a9-deficient rats (hyperexcretion of urine cystine, crystalluria and mild inflammatory renal pathology changes) resembles that of clinical cystinuria." (PMID 35416493, 2022). "Gene screens have found that mutations in SLC3A1 or SLC7A9 gene are responsible for most cases of cystinuria, for encoding defective cystine transporters." (PMID 36421847, 2022). "Mice deficient for either the Slc3a1 or Slc7a9 gene develop cystine urinary stones, corresponding to similar stone types in human cystinuria." (PMID 35771811, 2022). "Similar to human classic cystinuria, cystine hexagonal crystals were observed in the urine of Slc7a9-deficient rats, instead of common crystals (calcium oxalate crystal, calcium phosphate crystal and ammoniomagnesium phosphate crystal) in the urine of WT rats." (PMID 35416493, 2022). "This Slc7a9-deficient rats represent an ideal model to clarify the pathophysiology of cystinuria and to provide a favorable animal model for further clinical studies." (PMID 35416493, 2022). "The main objectives of the present study were to identify genetic mutations in SLC7A9 gene associated with cystinuria in Jordanian individuals." (PMID 33680451, 2021). "Mutations in the SLC7A9 gene are prevalent and can be used as molecular tools to diagnose cystinuria." (PMID 33680451, 2021). "We have previously reported 57 mutations in one of two genes (SLC3A1 and SLC7A9) in a large UK cohort of cystinuria patients." (PMID 33169184, 2021). "The main objectives of the present study were to identify genetic mutations in SLC7A9 gene associated with cystinuria." (PMID 33680451, 2021). "According to gene-based classification, type A and type B cystinuria are associated with mutations of both alleles of SLC3A1 or SLC7A9, respectively." (PMID 33262960, 2020). "SLC3A1 exit from the endoplasmic reticulum is facilitated by SLC7A9, and mutations in SLC7A9 also result in cystinuria." (PMID 31100816, 2019). "Based on genotyping, cystinuria can be classified as Type A (caused by mutations in SLC3A1) or Type B (caused by mutations in SLC7A9)." (PMID 31878022, 2019). "The cystinuria associated variant p.Val142Ala in SLC7A9 has an allele frequency of 31% indicating that it regularly occurs in individuals." (PMID 28812535, 2017). "From the clinical studies we identified a total of 94 SLC3A1 and 58 SLC7A9 cystinuria associated point mutations." (PMID 28812535, 2017). "Given the high frequency of this variant it is likely that it has a limited effect on SLC7A9 function as cystinuria is a rare disease, this is reinforced by the low evolutionary conservation of residue 142 in the protein (ConSurf score of 1)." (PMID 28812535, 2017). "Molecularly, mutations in the SLC3A1 gene cause type A cystinuria, while type B is due to SLC7A9 gene mutations." (PMID 28166740, 2017). "No significant clinical differences were detected in this study between type A (SLC3A1 variants) and type B cystinuria (SLC7A9 variant)." (PMID 28166740, 2017). "The results of this study are promising and highlight the areas of research which must now be pursued to better understand how mutations in SLC3A1 and SLC7A9 cause cystinuria." (PMID 28812535, 2017). "Using a literature search, we collated a set of 94 SLC3A1 and 58 SLC7A9 point mutations known to be associated with cystinuria." (PMID 28812535, 2017). "Across 49 studies, 58 and 94 cystinuria associated point mutations were identified in SLC7A9 and SLC3A1, respectively." (PMID 28812535, 2017). "In conclusion, we describe here novel models of cystinuria in a diversity of feline breeds, with unique SLC7A9 variants and clinical features." (PMID 27404572, 2016).
cystinuria (continued). "This study identifies the first SLC7A9 variants causing feline cystinuria and reveals that, as in humans and dogs, this disease is genetically heterogeneous in cats." (PMID 27404572, 2016). "Cystinuria is an inherited aminoaciduria caused by mutations in SLC7A9 and SLC3A1 that encode for the two subunits b0,+AT and rBAT, respectively." (PMID 26359869, 2015). "Cystinuria is an autosomal recessive disease caused by the mutation of either SLC3A1 gene encoding for rBAT (type A cystinuria) or SLC7A9 gene encoding for b0,+AT (type B cystinuria)." (PMID 25048459, 2014). "- BB (homozygosity for one or compound heterozygosity for two SLC7A9 mutations) is consistent with cystinuria." (PMID 22480232, 2012). "Mutations in the SLC3A1 and SLC7A9 genes lead to cystinuria, a hereditary disorder characterized by defective reabsorption of cystine and dibasic amino acids (lysine, arginine, and ornithine) in the kidney and intestine, resulting in recurrent cystine kidney stones." (PMID 41142409, 2025). "Here, we present two pediatric cases of cystinuria, both involving mutations in the SLC7A9 gene." (PMID 40981121, 2025). "Approximately 53% of individuals with cystinuria harbor mutations in SLC7A9, though prevalence may vary by population and screening methodology." (PMID 40981121, 2025). "Furthermore, MS increased the metabolites related to cystinuria, which is caused by defective in amino acid transporter, such as SLC7A9 and SLC3A1." (PMID 39259834, 2024). "To date, two genes, SLC3A1 and SLC7A9, have been identified as causes of cystinuria." (PMID 37893120, 2023). "Variants in SLC3A1 and SLC7A9 follow autosomal recessive inheritance and autosomal dominant inheritance with reduced penetrance, respectively, which complicates the interpretation of cystinuria-related variants." (PMID 37439839, 2023). "The activated GSH pathway in the kidney of cystinuria rat may explain the renal damage of Slc7a9-deficient rat and provide some clues regarding pathogenic and therapeutic directions." (PMID 35416493, 2022). "In addition, typical hexagonal cystine crystals can be observed in both cystinuria patients and our Slc7a9-deficient rat models." (PMID 35416493, 2022). "However, previous studies indicated to the existence of 30 mutations in SLC7A9 among cystinuria patients." (PMID 33680451, 2021). "Genetic polymorphisms in solute carrier family 7-member 9 (SLC7A9) gene, an amino acid transporter in renal proximal tubule cells, cause cystinuria, showing an association with GFR, and have been identified as a risk factor for CKD patients of European ancestry." (PMID 31534799, 2019). "Genetic polymorphisms in Solute Carrier Family 7 Member 9 (SLC7A9), an amino acid transporter known to be expressed in renal proximal tubule cells, cause cystinuria, are associated with GFR, and have been identified as a risk factor for CKD patients of European ancestry." (PMID 29665793, 2018). "Many mutations have been identified in both SLC3A1 and SLC7A9 in individuals with cystinuria." (PMID 28812535, 2017). "Importantly, this study shows how the experimental assessment of the impact on splicing of SLC3A1 and SLC7A9 variants contributed to the full molecular characterization of cystinuria." (PMID 28717662, 2017). "We report here the first SLC7A9 variants responsible for causing cystinuria in cats." (PMID 27404572, 2016). "Furthermore, despite the absence of an identified functional domain, variants in this region of SLC7A9 (p.Leu283Phe and p.Ser286Phe) also cause cystinuria in human patients." (PMID 27404572, 2016). "Interestingly, three mutations show a strong ethnic association: p.Val170Met is restricted to Libyan Jews where it accounts for all patients; p.Pro482Leu affects >84% of the identified SLC7A9 alleles in the Japanese cystinuria cohort." (PMID 22480232, 2012).
cystinuria (continued). "In the present study, mild kidney abnormalities of Slc7a9-deficient rats included slight dilatation of renal tubules in the cortical area and increased collagenous deposition around the kidney, which exactly corresponds to the evidence to the effect that cystinuria leads to chronic nephritis." (PMID 35416493, 2022). "Furthermore, it can be asked whether the detection of only one mutated allele in SLC3A1 or SLC7A9 is indeed sufficient to explain the cystinuria phenotype, or whether a second genomic variant in the same or another gene is required." (PMID 30342472, 2018). "Cystinuria (OMIM #220100) is an inherited autosomal recessive aminoaciduria due to pathogenic variants in the SLC3A1 (solute carrier family 3 member 1 OMIM #104614) or SLC7A9 (solute carrier family 7 member 9 OMIM # 604144) genes, encoding respectively for rBAT and b0, +AT." (PMID 28717662, 2017). "Cystinuria is an autosomal recessive disorder caused by mutations in the SLC3A1 and/or SLC7A9 genes, which encode subunits of the amino acid transporter responsible for reabsorbing cystine and dibasic amino acids in the renal proximal tubule." (PMID 40981121, 2025). "Cystinuria is caused by mutations in SLC3A1 and SLC7A9 genes, leading to defective cystine transport that result in stone formation typically beginning in the first two decades of life, with higher severity in males." (PMID 40786091, 2025). "Mutations in different subunits SLC7A9 and SLC3A1 have been linked to cystinuria, an autosomal recessive disease characterized by the development of kidney stones." (PMID 39917180, 2024). "Cystinuria results from variants in SLC3A1 and SLC7A9, which encode for solute carrier family 3 member 1 and solute carrier family 7 member 9, respectively, both of which are expressed in the PT." (PMID 38606357, 2024). "Cystinuria is a genetic disorder caused by defects in the b0,+ transporter system, which is composed of rBAT and b0,+AT coded by SLC3A1 and SLC7A9, respectively." (PMID 37439839, 2023). "This includes the IGFBP5 gene candidate variant for bald thigh syndrome in sighthounds, SLC7A9 and SLC3A1 gene variants associated with cystinuria in Bulldogs, as well as PDK4 and TTN gene risk variants for dilated cardiomyopathy (DCM) in Dobermans." (PMID 36848397, 2023). "According to the mutation types of these two genes, Dello Strologo reclassified cystinuria into type A (two mutations on SLC3A1), type B (two mutations on SLC7A9), and type AB (one mutation on each of SLC3A1 and SLC7A9)." (PMID 37525149, 2023). "In summary, we report ten cystinuria cases and the interpretation of variants identified in SLC3A1 and SLC7A9, which included a novel variant in each gene." (PMID 37439839, 2023). "In 2002, the International Cystinuria Consortium classified cystinuria based on mutations in different genes into type A (SLC3A1 mutations), type B (SLC7A9 mutations) and type AB (both the SLC3A1 and SLC7A9 mutations)." (PMID 38114997, 2023). "Since the discovery of the underlying genetic defects in cystinuria, a number of variants in SLC3A1 and SLC7A9 have been reported to cause cystinuria." (PMID 37439839, 2023). "In our cohort, only one patient remained genetically uncharacterized for the cystinuria-causing mutation in the SLC3A1 and SLC7A9 genes." (PMID 38138969, 2023). "Eight participants (0.93%) had a carrier status and heterozygous P/LP variants for AR diseases: CFTR cystic fibrosis, ITGB4 junctional epidermolysis bullosa type 5A, MEFV AR familial Mediterranean fever, and SLC7A9 AR cystinuria." (PMID 36635046, 2023). "Cystinuria is an autosomal recessive genetic disorder caused by two genes (i.e., SLC3A1 and SLC7A9)." (PMID 37115175, 2023). "While a number of variants have been discovered as a cause of cystinuria, interpretation of variants in SLC3A1 and SLC7A9 is still challenging." (PMID 37439839, 2023).